RPL3P2 (ribosomal protein L3 pseudogene 2)
Synonyms: RPL3-Hom; RPL3_1_679
Gene: Processed pseudogene on chromosome 6 (31,280,317 to 31,281,519, forward strand). Ensembl gene ENSG00000227939.
Diseases named in the same sentence as RPL3P2 in open-access papers:
RPL3P2 is named in the same sentence as 1 disease in open-access papers, as found by Europe PMC text mining. Sharing a sentence is not in itself a finding about the gene and the disease.
RPL3P2 shares sentences with these, for which no sentence is quoted: autosomal dominant polycystic kidney disease (1 paper).